IL4 (interleukin 4)
Diseases named in the same sentence as IL4 in open-access papers (continued):
Sharing a sentence is not in itself a finding about the gene and the disease.
breast carcinoma (continued). "Furthermore, IL‐1β, TNF‐α, and IL‐4 did mediate the relationship between psychological distress and cognitive function in breast cancer survivors." (PMID 36965094, 2023). "As in the heatmap, the liver and kidney function, coagulation factors and routine blood test results of 84 breast cancer blood samples were retrospectively analyzed to explore the correlation between the two cytokines, IL-4 and TNF-α, the statistically significant results are marked with *." (PMID 37007080, 2023). "Thus, in this model of breast cancer lung metastasis, IL4 potentiates an immunosuppressive Th2 environment through its actions on monocyte differentiation to MAMs after their recruitment via CCL2." (PMID 36077870, 2022). "Therefore, the high level of IL-4 and IL-10 expressing T cells in the spleen, as well as mLN at day 21, indicates systemic immune suppression at the late stage of breast cancer." (PMID 36232335, 2022). "Since circWWC3 up-regulates the expression and secretion of IL-4 in breast cancer cells, we postulated that circWWC3-mediated up-regulation of IL-4 secretion might affect the acquisition of tumor-promoting phenotypes of TAMs in breast cancer microenvironment." (PMID 35996149, 2022). "Taken together, our results indicated that circWWC3 could enhance PD-L1 expression of TAMs and breast cancer cells through up-regulating IL-4 expression and secretion to facilitate breast cancer immune escape." (PMID 35996149, 2022). "In the present study, we revealed that circular RNA circWWC3 could up-regulate the expression and secretion of IL-4 in breast cancer cells." (PMID 35996149, 2022). "CircWWC3 could augment breast cancer progression through promoting M2 macrophage polarization and tumor immune escape via regulating the expression and secretion of IL-4." (PMID 35996149, 2022). "Taken together, our results indicated that circWWC3 could induce M2-like TAM polarization through up-regulating IL-4 expression and secretion to promote the migration of breast cancer cells." (PMID 35996149, 2022). "In summary, our study suggested that IL-4 could promote M2 macrophage polarization and PD-L1 expression of TAMs and breast cancer cells." (PMID 35996149, 2022). "In the present study, we revealed that circWWC3 could up-regulate the expression and secretion of IL-4 in breast cancer cells." (PMID 35996149, 2022). "In our study, circWWC3 could enhance PD-L1 expression in TAMs and breast cancer cells through up-regulating IL-4 expression and secretion." (PMID 35996149, 2022). "It was previously shown that STAT6 sites could specifically bind STAT6 activated by IL4 in several cell lines, such as human breast cancer cells and normal human prostate epithelial cells (PrEC)." (PMID 36362361, 2022). "Though analyzing the expression of circWWC3, IL-4, PD-L1, and CD163 in 140 cases of breast cancer tissues, we found that high expression of circWWC3 was associated with poor overall survival and disease-free survival of breast cancer patients." (PMID 35996149, 2022). "By using qRT-PCR, western blot and ELISA assay, we confirmed that circWWC3 could up-regulate the expression and secretion of IL-4 in breast cancer cells." (PMID 35996149, 2022). "Moreover, up-regulated IL-4 also enhanced the expression of PD-L1 in breast cancer cells, which further facilitates breast cancer immune evasion." (PMID 35996149, 2022). "Cytokine IL-4 as a Th2 characteristic is accompanied by a poor prognosis for breast cancer." (PMID 36298611, 2022). "In this study, initial in vitro experiments demonstrated that macrophage phenotype affects migration of metastatic breast cancer cells, with anti-inflammatory phenotype (IL-4-stimulated) leading to increased migration compared to pro-inflammatory phenotype (LPS-stimulated)." (PMID 35359423, 2022). "Indeed, studies have documented that targeting M2 markers (e.g. IL‐4 and/or IL‐13) can reduce primary breast tumor burden and prevent breast cancer metastasis." (PMID 36325601, 2022).
breast carcinoma (continued). "Conclusively, circWWC3 might augment breast cancer progression through promoting M2 macrophage polarization and tumor immune escape via regulating the expression and secretion of IL-4." (PMID 35996149, 2022). "Furthermore, circWWC3 was positively correlated with the expression of IL-4 in breast cancer tissues." (PMID 35996149, 2022). "It is known that the level of IL-4 is higher in malignant tumors of the breast than in benign ones." (PMID 36286034, 2022). "In an experimental metastasis model that eliminates the contribution of the primary tumor, we determined that IL4 signaling in macrophages facilitates seeding of mammary tumor cells to the lung, thus suggesting a specific role for this cytokine at the metastatic site." (PMID 36077870, 2022). "On the other hand, the proliferation of breast cancer cells, retinal progenitor cells, human astrocytes, preadipocytes could be inhibited by IL-4, and it remained controversy on its effects on proliferation of B cells." (PMID 34863091, 2021). "The presence of macrophages and Th2-polarized CD4+ T cells limits the efficacy of radiotherapy for breast cancer, and eliminating these cells or neutralizing IL-4 may improve the clinical response to cytotoxic therapy in breast cancer patients." (PMID 34625124, 2021). "IL-4 is known to accelerate glucose and glutamine up-take and enhance their metabolism in immune cells and has recently been demonstrated to partake in metabolic reprogramming of breast cancer cells as well." (PMID 32512917, 2020). "Furthermore, distinct patterns of cytokines, including expression of IFN-γ, IL-4, and IL-10, have been observed in specific breast cancer groups compared to a healthy population." (PMID 32560316, 2020). "Anti-apoptotic activity of IL-4 has been confirmed also in thyroid, lung, and breast cancer." (PMID 32512917, 2020). "In addition, STAT3 knockdown or JAG1 knockdown reduced the secretion and protein expression of IL-4 and IL-6 in breast cancer cells, it also inhibited the proliferation of breast cancer cells." (PMID 32943090, 2020). "Additionally, studies examining IL-4 concentrations in the blood of breast cancer patients before starting treatment demonstrate a correlation between IL-4 and subsequent mortality." (PMID 31174326, 2019). "These include IL4, which is elevated in patients with breast cancer." (PMID 29747685, 2018). "We co-cultured GFP-firefly luciferase (eGFP-FFLuc) labeled MDA MB 468 breast cancer cells with either 1G or 1G.4/7ICR T cells at an effector-to-target (E:T) ratio of 1:10 in the presence of IL4 (400 U/mL), monitoring anti-tumor activity by bioluminescence imaging." (PMID 29747685, 2018). "In addition, the culture supernatant ofASCs isolated from breast cancer patients withpathological stage III had an ability to inducedifferent cytokines such as IL-4, TGF-β1 andIL-10 in PBLs and to upregulate CD4+CD25highFoxp3+ T regulatory cells." (PMID 28367424, 2017). "Thus, IR-induced IL-4 enhances primary breast cancer metastasis to lung by stimulating the expression of components related to mesenchymal traits, invasiveness, angiogenesis, stemness maintenance, and proliferation." (PMID 27895317, 2016). "Recent studies of IL-4/IL-4 receptor (IL-4R) signaling in breast cancer cells in vitro and in vivo show enhanced cell survival and proliferation via signal transducer and activator of transcription (STAT)/protein kinase B (AKT)/mitogen-activated protein kinase (MAPK) signaling." (PMID 27169366, 2016). "In addition to these effects on stromal cells, some studies have reported that IL-4 has antitumor functions by inducing apoptosis in several types of tumor cells including breast cancer, renal cell carcinoma, and hepatocellular carcinoma." (PMID 26989335, 2016). "This study provides evidence that IL-4 could provide therapeutic benefit in breast cancer treatment by suppressing both tumor growth and metastasis, in part through an immune modulatory effect on tumor-associated myeloid cells." (PMID 27563494, 2015).
breast carcinoma (continued). "The IL-4/IL-4R interaction enhanced the proliferation and survival of breast cancer cells in vitro." (PMID 26313265, 2015). "Our results show a marked increase in MMP-9 expression, as detected by gelatine zymography and real time RT-PCR, when RAW264.7 macrophages are exposed to the M2 polarization-inducing cytokine IL-4 or when they are co-cultured with breast cancer cells in separate chambers." (PMID 26078009, 2015). "We tested whether morphine modulates the activation of macrophages induced by (i) interleukin-4 (IL-4), the prototypical M2 polarization-inducing cytokine, or (ii) coculture with breast cancer cells." (PMID 26078009, 2015). "MiR-223, a miRNA specific for IL-4-activated macrophages, could be transported from macrophages to breast cancer cells via exosomes to promote breast cancer cell invasion via modulation of the β-catenin pathway." (PMID 25566500, 2014). "One of the important observations in our study was the recognition of inflammation related factors in the IPA network and a number of pathway showed IL-5, IL-1β, TNF, IL-4, and INFγ as the central molecules highlighting an already existing relationship between inflammation and breast cancer." (PMID 23216862, 2012). "To determine whether miRNAs released by IL-4-activated macrophages are shuttled into co-cultured breast cancer cells, we transfected macrophages with either Cy3-labeled miR-223 or non-mammalian lin-4 miRNA prior to co-culture with SKBR3 cells." (PMID 21939504, 2011). "Our study provides evidence for the delivery of invasion-potentiating miR-223 by IL-4-activated macrophages to breast cancer cells via exosomes and may highlight a novel communication mechanism between TAMs and cancer cells." (PMID 21939504, 2011). "Similarly, breast cancer cells preloaded with miR-223-ASO had decreased invasiveness when co-cultured with IL-4-activated macrophages." (PMID 21939504, 2011). "Moreover, the invasiveness of the co-cultivated breast cancer cells decreased when we treated IL-4-activated macrophages with miR-223-ASO." (PMID 21939504, 2011). "Moreover, when miR-223 expression in IL-4-activated macrophages was reduced, the invasiveness of co-cultivated breast cancer cells also decreased." (PMID 21939504, 2011). "Additionally, miR-223 is involved in cancer progression; therefore, we focused on miR-223 expression levels in breast cancer cells after co-cultivation with IL-4-activated MDMs." (PMID 21939504, 2011). "Upon PMA stimulation, the percentage of T lymphocytes expressing IL-4 was significantly higher in breast cancer patients than in controls (2.36 ± 0.49 vs 1.37 ± 0.16%, P=0.039), while the percentages of CD3+ cells expressing either IL-2 or IFN-γ were slightly decreased in cancer patients." (PMID 14562018, 2003). "Notably, serum IL-4 levels significantly increased (p = 0.001), and IL-12 levels also rose significantly (p = 0.03) in the beta glucan group, suggesting its potential as an immunomodulatory adjunct in breast cancer treatment." (PMID 40290044, 2025). "Moreover, IL-4 is increased in breast cancer patients with cognitive impairment." (PMID 36386524, 2022). "Thus, circWWC3 might augment breast cancer progression through promoting M2 macrophage polarization and tumor immune escape via regulating the expression and secretion of IL-4." (PMID 35996149, 2022). "In addition, miR-223, which is secreted by IL-4-activated macrophages, could be delivered to breast cancer cells, and further facilitate breast cancer cell invasion, which is mediated by TAMs." (PMID 35986343, 2022). "In addition, increased IL-4 expression and secretion could induce the expression of PD-L1 in breast cancer cells and M2 macrophages, which further facilitated breast cancer immune evasion." (PMID 35996149, 2022). "In addition, increased secretion of IL-4 from breast cancer cells could induce the expression PD-L1 in M2 macrophages." (PMID 35996149, 2022).
breast carcinoma (continued). "It was revealed that in a co-culture system, uptake of exosomes secreted from IL-4 stimulated macrophage could stimulate the invasion of breast cancer cells and interruption of the Mef2c-β-catenin pathway due to uptake of miR-223 (miRNA signature for IL-4 activated macrophages)." (PMID 32346400, 2020). "Additionally, IL-4 level is high in breast cancer patients who died from ER−/PR− tumors." (PMID 31014367, 2019). "Notably, not only the proportion but also total cell numbers of IL-4+CD4+ cells remained in a relatively low level among TILs during the breast cancer development, suggesting that Th2 subset is a subdominant subset compared with the other T cell subsets ( < 4%)." (PMID 25968569, 2015). "In a co-culture system, it was demonstrated that uptake of IL-4 activated macrophage secreted exosomes could promote the invasion of breast cancer cells, due to uptake of miR-223 (a microRNA specific for IL-4 activated macrophages) and disruption of the Mef2c-β-catenin pathway." (PMID 23839094, 2013). "IL-4 has been shown to have a modest but direct inhibitory effect on the growth of tumor cells of hematopoietic and nonhematopoietic origin in vitro and in vivo, including those derived from human melanoma, non-Hodgkin’s malignant B-lymphoma, and colon, renal, gastric, and breast carcinoma." (PMID 21686188, 2011). "By using PMA, IL-4, and IL-13, we successfully induced THP-1 cells into M2-like macrophages, which subsequently promoted breast cancer cell proliferation and inhibited apoptosis, accompanied by increased JMJD3 expression." (PMID 41955245, 2026). "The concentrations of anti-inflammatory cytokines IL-4 and IL-10 increased maximally in the subgroups of HER2-positive breast cancer: luminal B(+) (+108.1%, p = 0.0006 and +163.6%, p = 0.0000) and non-luminal (+105.6%, p = 0.0015 and +142.7%, p = 0.0000)." (PMID 40429927, 2025). "Obesity has little effect on mammary tumor incidence in rodents before OVX, but after OVX, obesity leads to more tumors and reduced anti-inflammatory cytokines (IL-2, IL-4)." (PMID 40584290, 2025). "In a randomized controlled trial (KCT0000939), desflurane was found to be beneficial to the immune response by maintaining the IL-2/IL-4 and CD4+/CD8+ T-cell ratios in breast cancer patients, providing an immune protective response." (PMID 40584290, 2025). "A cohort study done in in early-stage breast cancer patients investigated the changes in cytokine (IL-1β, TNF-α and IL-4) levels before and after chemotherapy demonstrated higher IL-4 levels in patients after receiving the chemotherapy treatment." (PMID 39355088, 2024). "In contrast, the chronic inflammatory IL signature, including IL-4, IL-5, IL-10, IL-13, IL-17, and CXCL1, showed a significant prognostic effect across the whole cohort of breast cancer patients." (PMID 39456897, 2024). "We found that IL4 induced the phosphorylation of AKT and ACLY in both human and murine mammary cancer cell lines." (PMID 38731867, 2024). "In both training and validation cohorts, we found that the riskscore for IL-4 and TNF-α had a detrimental effect on overall survival in breast cancer." (PMID 37007080, 2023). "In summary, we have developed a nomogram based on two cytokines including IL-4 and TNF-α to predict OS of breast cancer and investigated their correlation with blood test indicators." (PMID 37007080, 2023). "Our results found that breast cancer survivors with psychological distress showed significantly higher levels of IL‐1β, TNF‐α, and IL‐4." (PMID 36965094, 2023). "In breast cancer cell lines, positive feedback was reported between the upregulated expression of 3β-HSD1 and the expression of IL-4 in ER-positive and ER-negative breast cancer cells." (PMID 36614002, 2022). "Through co-cultured with breast cancer cells-conditioned medium, THP-1 cells were confirmed to incline to M2 phenotype at the present of circWWC3 at an IL-4-dependent manner." (PMID 35996149, 2022).
breast carcinoma (continued). "In three murine breast cancer models (EO771, 4T1 and EMT6), IPD significantly inhibited the IL-4 secretion by Th2 cells, promoted Th2 to Th1 switching, remodeled the immune landscape and inhibited tumor growth." (PMID 36564797, 2022). "In order to further pinpoint the role of TAMs in microcalcifications of breast cancer cells, THP-1 cells were treated with PMA and IL-4 to induce differentiation into M2-like TAM which was verified by CD68 and CD163 expression (M2-like phenotype biomarker)." (PMID 34983451, 2022). "A recent study has shown that macrophages stimulated by IL4 and IL13 promoted invasion of breast cancer cells through Rho-GTPase regulation." (PMID 35207737, 2022). "Moreover, increased IL-4 could indicate aggravated cognitive impairment in breast cancer patients." (PMID 36386524, 2022). "The aim of this study was to test the efficacy of QBX258, a monoclonal IL4/IL13 neutralizing antibody, in women with breast cancer–related lymphedema (BCRL)." (PMID 34571811, 2021). "The interleukin-4 (IL4)/IL4Rα immune signaling axis is a direct promoter of survival and proliferation in breast cancer cells." (PMID 31936350, 2020). "To determine the Th2 lymphocyte phenotype in the canine mammary tumors, we assessed the expression of CCR2, GATA3, and IL-4." (PMID 32225066, 2020). "Using an orthotropic breast cancer xenograft model in NOD/SCID mice, IL-4-treated THP-1 or THP-1/shCXCL1 cells were co-injected with MDA-MB-231 cancer cells into the mammary fat pads of NOD/SCID mice at a ratio of 1:3." (PMID 30158589, 2018). "Evidence indicates that AdSCs release IL-4, IL-8, IL-10, matrix metalloproteinase (MMP)-2, VEGF and SDF-1, which potentiate breast cancer growth and progression." (PMID 28750689, 2017). "Macrophages were freshly isolated from human breast cancer tissues (primary TAMs) or derived from monocytes (monocyte-derived macrophages, MDMs) that were activated by IL-4 treatment, or coculture with MDA-MB-231 or primary breast cancer cells." (PMID 26416449, 2015). "Prior to co-cultivation, IL-4-activated macrophages were transfected with either control (NC) or lin-4 miRNA, and SKBR3 breast cancer cells were transfected with a luciferase reporter gene with a lin-4 target sequence at its 3'-UTR." (PMID 21939504, 2011). "Deletion of ST2 in BALB/c mice bearing mammary carcinoma attenuated tumor growth and metastasis, which was accompanied by increased serum levels of IL-17, IFN-γ, and TNF-α and decreased IL-4." (PMID 21484786, 2011). "Our findings of elevated IL-4 levels in non-responders to neoadjuvant chemotherapy in LuminalB/HER2 + breast cancer align with previous research demonstrating IL-4’s role in promoting tumor survival and chemotherapy resistance." (PMID 41366282, 2025). "Conversely, an independent case–control study observed significantly lower levels of circulating IL-4 in breast cancer patients, while IL-2 did not significantly differ from those of the controls." (PMID 41150099, 2025). "Taken together, these data suggest that during breast cancer recurrence, tumor cell-derived OPN recruits macrophages into the tumor and, together with tumor cell-derived IL-4, further accentuates some of their pro-tumorigenic characteristics such as IL-4R expression to facilitate recurrence." (PMID 39448577, 2024). "Breast cancer patients with psychological distress displayed poor cognitive function, poor memory, and inferior quality of life, which was accompanied by higher cytokine levels of IL‐1β, TNF‐α, and IL‐4." (PMID 36965094, 2023). "Peripheral blood samples were collected from 187 rural working women with breast cancer, occupationally exposed or not to pesticides, to quantify the levels of cytokines IL-1β, IL-12, IL-4, IL-17-A, and TNF -α." (PMID 37942322, 2023). "CD4+T cells could increase the secretion of IL4, IL2 promoting breast cancer progression, and the mature dendritic cells induced the proliferation of CD4+T cells." (PMID 36644231, 2023).